ALK (ALK receptor tyrosine kinase)
Diseases named in the same sentence as ALK in open-access papers (continued):
Sharing a sentence is not in itself a finding about the gene and the disease.
neutropenia (5 papers, 2018 to 2025). A decrease in the number of neutrophils found in the blood. "For ALK inhibitors, only one case report has described an association between the occurrence of neutropenia and improved progression-free survival with crizotinib treatment." (PMID 37894307, 2023). "Between 0 and 26% of patients treated with second- and third-generation ALK inhibitors have been reported to exhibit neutropenia of any grade, and between 0 and 20% of patients have been reported to have grade 3 and 4 neutropenia." (PMID 37894307, 2023). "Due to its rarity, very few data on the management of neutropenia during treatment with ALK inhibitors are available." (PMID 37894307, 2023). "Only one retrospective study of 36 patients showed a prognostic role for neutropenia induced by ALK inhibitors." (PMID 37894307, 2023). "When looking at the data for third-generation ALK inhibitors, all grades of neutropenia have been observed in between 0 and 7% of cases." (PMID 37894307, 2023). "In view of the data in the literature, we propose the management of neutropenia induced by ALK inhibitors." (PMID 37894307, 2023). "In the phase 1 study in children with ALK-positive tumours, crizotinib dose reductions due to toxicity were reported for four patients with grade 4 neutropenia." (PMID 37894307, 2023). "Our literature review aims to improve the knowledge of ALK inhibitor-induced neutropenia in order to improve their management." (PMID 37894307, 2023). "Among them, neutropenia induced by ALK inhibitors has been reported, but its incidence and management are not addressed in recommendations." (PMID 37894307, 2023). "Neutropenia is one of the most common side effects of crizotinib treatment, as shown in the data from a phase 1 study of crizotinib in ALK-positive NSCLC patients." (PMID 37894307, 2023). "Neutropenia is more frequent with first-generation ALK TKIs than with second- and third-generation TKIs." (PMID 37894307, 2023). "Few data are available on neutropenia induced by ALK inhibitors and on the pathophysiological mechanism and therapeutic adaptations necessary to continue the treatment." (PMID 37894307, 2023). "Febrile neutropenia has been reported in 0 to 10% of patients treated with first- and second-generation ALK inhibitors." (PMID 37894307, 2023). "Neutropenia induced by ALK inhibitors is a common side effect of first-generation therapies and less common with second- and third-generation therapies." (PMID 37894307, 2023). "Here, we have reviewed the data from published clinical studies and case reports to provide an overview of neutropenia induced by ALK inhibitors." (PMID 37894307, 2023). "We performed a systematic review of neutropenia induced by ALK inhibitors to assess the incidence of grade 3–4 and febrile neutropenia and to assess data on the management of this toxicity." (PMID 37894307, 2023). "Neutropenia induced by ALK inhibitors is sometimes responsible for treatment interruption and may require dose reduction." (PMID 37894307, 2023). "In our systematic review, 51 articles on ALK inhibitor-induced neutropenia were reviewed." (PMID 37894307, 2023). "Furthermore, the incidence of neutropenia induced by second-generation ALK inhibitors like ceritinib, alectinib, and brigatinib or third-generation ALK inhibitors like lorlatinib is minimal." (PMID 37894307, 2023). "Regarding second-generation ALK inhibitors, in a real-world surveillance study of alectinib in Japan, grade 1 neutropenia was reported in 50/1221 patients (4.1%), grade 2 neutropenia events in 41/1221 patients (3.4%), and grade ≥ 3 neutropenia events in 14/1221 patients (1.1%)." (PMID 37894307, 2023). "There are few data on the management of neutropenia induced by ALK inhibitors." (PMID 37894307, 2023). "Moreover, in all studies comparing ALK inhibitors to chemotherapy, neutropenia remained more common in those treated with chemotherapy." (PMID 37894307, 2023).
neutropenia (continued). "Grade 3 or 4 AEs were neutropenia (n = 9), lymphopenia (n = 6), hypophosphatemia (n = 6), raised alanine aminotransferase (n = 6), results interpreted that Crizotinib is well tolerated with durable, rapid responses in patients with ALK-positive NSCLC." (PMID 34150615, 2021). "These off-target effects of ALK inhibitors may explain the reported neutropenia." (PMID 37894307, 2023). "In a phase 1 study of crizotinib in ALK-positive NSCLC patients, 20% of patients needed a dose reduction because of neutropenia (n = 2)." (PMID 37894307, 2023).
ovarian tumor (5 papers, 2019 to 2024). "The lung and ovary tumor both showed marked anaplastic lymphoma kinase gene (ALK) protein expression by immunohistochemistry." (PMID 37780910, 2023). "As ROR2 targeting approaches for other cancers are under development (including lung and ovarian tumors), our findings suggest that ALK+ ALCL cases with resistance to current therapies may also benefit from ROR2 targeting strategies." (PMID 35246138, 2022). "Zhai and colleagues reported that APG-2449, a novel ALK/ROS1/FAK inhibitor, is effective against human ovarian tumor either alone or in combination with other therapies." (PMID 37875515, 2023). "In this regard, the current phase 1–2 trials of ADC antibody and CART targeting ROR2 for other tumor types (e.g., NSCLC and ovarian tumors: ClinicalTrials.gov #NCT03504488, NCT03960060, NCT03393936,) may also benefit ALK+ ALCL patients." (PMID 35246138, 2022). "While the testicular tumors were not tested for ALK and MUC4, recent reports of histologically similar ovarian tumors confirmed MUC4 expression." (PMID 39031200, 2024).
peritoneal mesothelioma (5 papers, 2022 to 2026). A benign or malignant mesothelial neoplasm that arises from the peritoneum. "In 0.36% of pleural mesothelioma patients and 1.13% of peritoneal mesothelioma patients, we detected ALK rearrangements and short variant alterations." (PMID 36138075, 2022). "A retrospective study of 88 patients with peritoneal mesothelioma demonstrated a low prevalence of ALK fusions (3/88, 3.4%), including 1 in a novel and previously unreported fusion partner (ATG16L1)." (PMID 38136262, 2023). "We have previously reported the case of a patient with peritoneal mesothelioma harbouring an ALK translocation." (PMID 36138075, 2022). "Crizotinib showed clinical activity in some of the ALK-rearranged peritoneal mesotheliomas." (PMID 38136262, 2023). "The authors found unique ALK rearrangements in 3 peritoneal mesotheliomas." (PMID 36556334, 2022).
pleural mesothelioma (5 papers, 2018 to 2026). A neoplasm that arises from the mesothelial cells of the pleura. "Rare ALK (STERN-ALK most frequent) and EWSR1 (EWSR1-ATF1 or EWSR1/FUS-CREB) fusions have been observed in pleural mesothelioma of young patients." (PMID 39030439, 2024). "Interestingly, the same work reported gene fusions such as EWSR1-ATF1 and FUS-ATF1 and ALK rearrangements that are hardly found in pleural mesothelioma and seem to be specific for young women as compared to ALK-wild type patients but might respond to targeted treatment." (PMID 34249695, 2021).
retinoblastoma (5 papers, 2014 to 2024). A malignant tumor that originates in the nuclear layer of the retina. "Three genes from the ‘cancer’ and ‘neuro’ group are overlapping (ALK, TLX2, THY1), with THY1 being also directly connected to retinoblastoma." (PMID 39695086, 2024).
Spitz nevi (5 papers, 2014 to 2025). "Spitz nevi demonstrate strong S100 and Melan A positivity while lacking ALK rearrangement." (PMID 40688914, 2025).
visual disorders (5 papers, 2015 to 2024). "The next-generation ALK inhibitors exhibit ophthalmic side effect profiles comparable to those of crizotinib, but with lower incidence rates of visual disorders." (PMID 39728071, 2024). "Prescribing information for more recently approved ALK-inhibitors—ceritinib, lorlatinib, entrectinib, and alectinib—report vision disorders in 4.6% to 21% of patients, including blurred vision, photopsia, and diplopia." (PMID 38345654, 2024). "Both crizotinib and alectinib inhibit ALK at nanomolar concentrations, but the incidence of visual disorder is higher for crizotinib." (PMID 26271036, 2015). "In recent studies examining patients treated with alectinib, which is a newly established and more specific inhibitor of ALK, the frequency of adverse effects (including visual disorders) was significantly lower than that for crizotinib." (PMID 26271036, 2015). "The cumulative clinical trials in patients with advanced ALK- or ROS1-rearrangement NSCLC indicate that crizotinib has significant antitumor activity and a tolerable safety profile, with mild or moderate adverse events of visual disorders, diarrhea, nausea, and vomiting." (PMID 36330497, 2022). "Therefore, the high frequency of visual disorder induced by crizotinib is unlikely to be attributable to ALK inhibition." (PMID 26271036, 2015).
abscess (4 papers, 2019 to 2025). An inflammatory process characterized by the accumulation of pus within a newly formed tissue cavity which is the result of a bacterial, fungal, or parasitic infection or the presence of a foreign body. "There was a case of ALK+ NSCLC with BM presented with MRI features resembling an abscess." (PMID 38881327, 2024). "When a brain lesion suggestive of abscess develops in a patient with ALK-positive NSCLC, aspiration may be necessary to differentiate metastasis from abscess." (PMID 31316849, 2019).
acinar adenocarcinoma (4 papers, 2019 to 2021). "At diagnosis, there were 83 (72.8%) stage I/II patients, 76 (66.7%) with acinar adenocarcinoma, and a total of 48 (42.1%) cases and 14 (12.3%) patients with EGFR mutations and other mutations, including KRAS and ALK, respectively." (PMID 32154654, 2020).
acute kidney injury (4 papers, 2015 to 2024). Sudden and sustained deterioration of the kidney function characterized by decreased glomerular filtration rate, increased serum creatinine or oliguria. "ALK inhibitors have been associated with the occurrence of acute kidney injury and chronic kidney disease in clinical practice." (PMID 39026680, 2024). "We report a rare case in which acute renal failure and congestive heart failure occurred after the administration of crizotinib for lung AC with ALK rearrangement, and in which dose and schedule modification were required." (PMID 25899913, 2015).
anemia (4 papers, 2022 to 2026). A reduction in the number of red blood cells, the amount of hemoglobin, and/or the volume of packed red blood cells. "In terms of safety, as emerged from metanalyses, the spectrum of toxicities of ALK-TKIs differed, with anemia and constipation being more frequent with alectinib, whereas changes in lipid levels were the most frequent AEs associated with lorlatinib." (PMID 39001519, 2024).
angiomatoid fibrous histiocytoma (4 papers, 2021 to 2024). "Specifically, MAP3K8 and ALK presented PAX8+ papillary proliferations, ESWR1/FUS::ATF1 and EWSR1::YY1 displayed angiomatoid fibrous histiocytoma-like patterns, while SUFU showcased ‘tissue culture’-like spindle cell proliferation." (PMID 39059063, 2024).
Anxiety (4 papers, 2017 to 2024). Intense feelings of nervousness, tension, or panic often arise in response to interpersonal stresses. "ALK, a receptor tyrosine kinase, has previously been implicated in a number of psychiatric conditions – schizophrenia, depression, anxiety, and AUDs/SUDs." (PMID 28860990, 2017). "The expression of ALK, together with LTK, in the hippocampus and amygdala is associated with memory and anxiety." (PMID 37892172, 2023). "Interestingly, ALK KO mice show enhanced cognitive performance and reduced anxiety, while LTK KO mice do not show any significant changes." (PMID 37892172, 2023).
colorectal adenocarcinoma (4 papers, 2015 to 2024). The most common type of colorectal carcinoma. "Anaplastic lymphoma kinase (ALK) gene is directly related to colorectal adenocarcinoma, and may affect treatments for advanced CRC." (PMID 30397551, 2018).
Erdheim-Chester disease (4 papers, 2023 to 2025). "We also present an illustrative case of an ultra-rare neoplasm---Erdheim Chester Disease (non-Langerhans histiocytosis) ---with an ALK fusion, and brain involvement, remarkably responsive to an ALK inhibitor." (PMID 37773318, 2023).
gastric adenocarcinoma (4 papers, 2022 to 2025). "Gastric adenocarcinoma patients with higher expression of ALK gene had a lower survival probability compared to the low expression of ALK group (p = 0.0045)." (PMID 36145589, 2022). "In summary, we hypothesize that ALK gene overexpression can be a promising biomarker for prognosis and therapeutic management of gastric adenocarcinoma." (PMID 36145589, 2022). "We hypothesize that ALK gene overexpression can be a promising biomarker for gastric adenocarcinoma." (PMID 36145589, 2022). "Our hypothesis is that ALK gene overexpression can be a therapeutic target and/or a prognosis biomarker for patients with high-grade gastric adenocarcinoma." (PMID 36145589, 2022). "Interestingly, a novel form of ALK gene fusion was identified, being the first gastric adenocarcinoma case with RAB10-ALK fusion." (PMID 36145589, 2022). "In our cohort of nearly 500 gastric adenocarcinomas, no cases with ALK or NUT expression could be detected." (PMID 35204520, 2022). "However, ALK overexpression in gastric adenocarcinoma has not been well investigated." (PMID 36145589, 2022). "This study addressed this issue and analyzed the frequencies of ALK, TRK, and NUT alterations in gastric adenocarcinomas with or without neoadjuvant CTx." (PMID 35204520, 2022).
lung NET (4 papers, 2022 to 2024). "In this study, they reported two metastatic lung NET patients with ALK rearrangement received rapid response to alectinib." (PMID 39667359, 2024).
lymphoproliferative disorder (4 papers, 2012 to 2024). "Fine needle aspiration suggested a lymphoproliferative disorder, with biopsy and immunohistochemistry confirming primary cutaneous ALCL (CD30-positive, anaplastic lymphoma kinase [ALK]-negative)." (PMID 39877763, 2024).
malignant peritoneal mesothelioma (4 papers, 2021 to 2025). An aggressive malignant mesothelioma that arises from the peritoneum. "Recently, pediatric malignant peritoneal mesothelioma cases have been genetically studied, with alterations observed in ALK, EWSR1, FUS1, YY1, or in AURKA, AURKC, HLA-1B, ZNF-217, OR5F1, and MEN1 genes, but not in BAP1." (PMID 40725095, 2025). "Recent works have highlighted the presence of Anaplastic Lymphoma Kinase (ALK) gene alterations in a subgroup of MPM, similarly to peritoneal malignant mesothelioma occurring in young patients, then representing a novel pathogenetic event and a formidable target for specific ALK inhibitors." (PMID 34070888, 2021).
meningeal carcinomatosis (4 papers, 2021 to 2024). "Our results suggest that lorlatinib could be considered in patients with meningeal carcinomatosis resistant to second-generation ALK inhibitors, even when they exhibit serious symptoms associated with meningeal carcinomatosis." (PMID 34596160, 2021). "Consequently, ALK-positive patients tend to have a higher incidence of new intracranial lesions due to the long-term survival, associated with a relatively higher incidence of neurological death due to meningeal carcinomatosis." (PMID 35047245, 2021). "In this retrospective study, ALK-positive NSCLC patients with brain metastases (BM) or leptomeningeal metastases (LM) from six hospitals in China were divided into three cohorts based on the treatment history before the administration of alectinib." (PMID 35039026, 2022). "Here we have reported the successful treatment with lorlatinib of a patient with ALK-positive NSCLC who develop meningeal carcinomatosis." (PMID 34596160, 2021). "The frequency of neurological death due to meningeal carcinomatosis was relatively higher in long-term survival in ALK-positive patients than in EGFR-positive and wild type patients, although the difference was not significant." (PMID 35047245, 2021). "The present report indicates that lorlatinib is an effective treatment option for patient with ALK-positive NSCLC who develop meningeal carcinomatosis resistant to second-generation ALK inhibitors." (PMID 34596160, 2021). "Lorlatinib is an effective treatment option for patient with ALK-positive NSCLC who develop meningeal carcinomatosis resistant to second-generation ALK inhibitors." (PMID 34596160, 2021). "However, there is limited information about the activity of lorlatinib in ALK inhibitor-resistant meningeal carcinomatosis." (PMID 34596160, 2021).
meningioma (4 papers, 2013 to 2023). A generally slow growing tumor attached to the dura mater. "The histiocytes were positive for CD68, CD163, and ALK, and negative for EMA, PR, and SSTR2, which ruled out the diagnosis of meningioma." (PMID 36915094, 2023).
myelodysplastic syndrome (4 papers, 2010 to 2024). A clonal hematopoietic disorder characterized by dysplasia and ineffective hematopoiesis in one or more of the hematopoietic cell lines. "For example, chromosomal translocations involving NUP358 gene with FGFR1 lead to myelodysplastic syndrome/myeloproliferative neoplasms (MDS/MPNs), while NUP358 fusions with ALK are associated with acute myeloid leukemia." (PMID 38838144, 2024).
myeloid neoplasm (4 papers, 2010 to 2024). Proliferation of myeloid cells originating from a primitive stem cell. "Therefore, we suggest examining ALK rearrangement and using crizotinib in patients with a refractory or relapsed myeloid neoplasm and chromosome 2p23 aberration." (PMID 27494825, 2016).
schizophrenia (4 papers, 2011 to 2025). A major psychotic disorder characterized by abnormalities in the perception or expression of reality. "One human study has shown an association of polymorphisms in ALK with schizophrenia in a Japanese population, suggesting that ALK potentially affects the development of psychiatric disorders." (PMID 21799923, 2011). "Interestingly, the ALK marker rs1881421 in humans, which appears to be associated with body sway in response to an alcohol challenge, is also associated with schizophrenia in a Japanese population, implicating ALK in other neuropsychiatric diseases beyond AUDs." (PMID 21799923, 2011).
serous ovarian carcinoma (4 papers, 2015 to 2025). "This article reports a case of EML4‐ALK‐positive advanced low‐grade serous ovarian cancer (LGSOC) with intracranial metastasis that responded dramatically to a third‐generation ALK inhibitor, lorlatinib, with good therapeutic effect." (PMID 39780907, 2025). "This will become the first clinical evidence suggesting that ALK inhibitors may be an effective treatment for EML4‐ALK+ low‐grade serous ovarian cancer with intracranial metastasis." (PMID 39780907, 2025).
Thromboembolism (4 papers, 2022 to 2025). The formation of a blood clot inside a blood vessel that subsequently travels through the blood stream from the site where it formed to another location in the body, generally leading to vascular occlusion at the distant site. "A cohort study revealed that the highest incidences of thromboembolism were observed in patients with ALK-mutant NSCLC (43.5%) followed by patients with EGFR-mutant cancers (21.2%) and wild-type cancers (17.2%)." (PMID 41426325, 2025). "A recent meta-analysis confirmed that there is an increased incidence of thromboembolism in ALK+ NSCLC patients as compared to non-ALK+ patients." (PMID 35463328, 2022).